IL10 (interleukin 10)
Diseases named in the same sentence as IL10 in open-access papers (continued):
Sharing a sentence is not in itself a finding about the gene and the disease.
melanoma (continued). "Reflecting the low IL-10 secretion from the RhS skin model without the melanoma cells (assessed by ELISA), basal expression of IL-10 mRNA was found in keratinocytes and fibroblasts in the RhS." (PMID 32507967, 2020). "Interestingly, in the presence of IFNγ and TNFα melanoma cells can also upregulate TGFB, IL10, VEGFA, and VEGFC genes, which can further modulate the immunosuppressive phenotype of TAMs." (PMID 32793228, 2020). "Transcripts for IFN-g, IL-10 and IL-32 g were over-expressed in PD-L1+ compared to PD-L1(−) melanoma biopsies; in vitro, IL-10 and IL-32 g induced PD-L1 expression on Monos but not on melanoma cells." (PMID 31730010, 2019). "Moreover, during melanoma progression, the upregulation of miR-30d expression together with the reduced expression of GALNT7 enhances the secretion of IL-10 (interleukin 10) and decreases immune cell activation and recruitment." (PMID 30866509, 2019). "The proportion of Tregs induced by H-1PV infected and non-infected Sk29Mel-1 melanoma cells was similar as well as the release of IL-10." (PMID 31192129, 2019). "Other studies of malignant glioma and melanoma have shown that this treatment restores CD4+ and CD8+ effector T cells by abrogation of the immunosuppressive effect of Tregs which express these inhibitory markers and produce immunosuppressive IL-10 cytokine." (PMID 29610255, 2018). "In the B16 melanoma subcutaneous tumor model, CQ treatment consistently upregulated iNOS, while downregulating Arg1 in melanoma-infiltrating macrophages, concomitant with the increased expression of IFN-γ, IL-12p40, IL-12p35, and TNF-α, and downregulation of IL-10 in tumor tissues." (PMID 29491374, 2018). "Furthermore, a reduced secretion of IL-10 and IL-6, and of VEGF by melanoma cells has been reported within the tumor milieu." (PMID 29285320, 2017). "In addition, Tregs are deregulated in melanoma and inhibit the immune system through TGF-Δ, IL-10 and IDO over-production which dampens the activity of CD4+ and CD8+ lymphocytes, and NK cells." (PMID 29285320, 2017). "Forced expression of IL-10 in human melanoma cells did not enhance tumor growth and metastatic potential in nude mice, but rather significantly inhibited their tumorigenicity and metastatic capabilities." (PMID 29219852, 2017). "Here we did not observe any significant changes in IL-10 expression in the melanoma cell lines studied relative to normal melanocytes." (PMID 26631117, 2015). "IL-10 induction by TLR agonists has been observed in mouse models of breast cancer and melanoma." (PMID 24624132, 2014). "Restitution of IL-10 in the A375P human melanoma cell line, which does not produce endogenous IL-10, using a vector containing murine IL-10 cDNA, reverted tumor growth and lung metastases." (PMID 24901008, 2014). "Both IL-10 and TGF-ß have been previously shown to be expressed in melanoma." (PMID 24130734, 2013). "On one hand, IL-10 could hamper angiogenesis and tumor growth in mice bearing VEGF-producing ovarian cancer, and suppress tumor growth and metastasis of human melanoma cells." (PMID 23967403, 2013). "In these mice, the tumours grew slower than in control mice and behaved in a similar way to those induced by nontransfected tumour cells, confirming that IL-10 secreted by transfected cells is actually promoting the tumour growth in a melanoma-B16 model." (PMID 22220169, 2012). "In addition to Tregs, the levels of TGF-β IL-10, and autoantibodies (ANA, ACA, anti-dsDNA, and anti-HTG) were measured in serum samples collected from 14 of the 22 patients with melanoma undergoing IFN-α 2b treatment in this study." (PMID 20712892, 2010). "Similarly, plasma IL-10, an anti-inflammatory cytokine, was also significantly higher in melanoma groups, with and without combi-ICI therapy." (PMID 40313772, 2025).
melanoma (continued). "Furthermore, melanoma cells utilize multiple strategies to evade immune surveillance, including the secretion of immunosuppressive cytokines like transforming growth factor-beta (TGF-β) and interleukin-10 (IL-10)." (PMID 41394861, 2025). "Melanoma responds to this pro-inflammatory response by releasing suppressive mediators including CSF1, TGF-β, and CCL2, which reprogram micro-glial cells to become trophic, anti-inflammatory cells characterized by increased expression of Arg1, IL-10, and PD-L1." (PMID 41463339, 2025). "Additionally, in an experiment applying temozolomide to treat melanoma mice, it was found that exocytic vesicles exfoliated by melanoma cells post-treatment polarize macrophages towards the M2 phenotype by upregulating M2-like genes such as ARG-1 and IL-10." (PMID 38787372, 2024). "Furthermore, since IL-10 does not seem widely expressed across different melanoma cell lines, the increased secretion noted in the 624Mel cell line needs to be considered as an exception." (PMID 39736644, 2024). "For the treatment of melanoma, hydroartemisinin could significantly reduce the levels of p-STAT3, p65, and IL-10 induced the p-STAT1 both in vitro and in vivo, indicating that dihydroartemisinin exhibits anticancer effects on melanoma by affecting STAT1/STAT3 pathway." (PMID 39202965, 2024). "When the melanoma cells lacking IL-10 expression were admixed with the transfected cells, tumor growth and metastasis remained diminished, confirming that the anti-tumorigenic activity was IL-10-dependent." (PMID 38928185, 2024). "Dedifferentiation renders 624Mel melanoma cells hypersensitive to IFNγ stimulation in a context-dependent manner, resulting in non-additive upregulation of IFNγ-induced genes, increased PD-L1 protein expression and amplified secretion of CCL2, CXCL10 and IL-10." (PMID 39736644, 2024). "Thus, the downregulation of IL6, IL10, IL12, sICAM-1, sICAM-3, sPECAM-1, and CD40L secretion may lead to the melanoma progression and impair survival of the patients with metastatic melanoma." (PMID 35327461, 2022). "IL6 activates the antitumor immunity, regulates the secretion of the anti-inflammatory cytokine IL10 in the melanoma cells via the PI3K and ERK related pathways, and promotes the E/P-selectin- and ICAM-1-dependent extravasation of the cytotoxic T cells in melanoma lesions in vivo." (PMID 35327461, 2022). "Through the secretion of IL-10, these B cells can attenuate TH1, TH2 or TH17 cell-mediated immune responses in murine models of autoimmune, inflammatory and infectious diseases and inhibit anti-tumor cytotoxic T cell responses in mouse models of colorectal cancer and melanoma." (PMID 34359321, 2021). "Using single-cell suspensions prepared from malignant melanoma resections banked at MSK and classified as low or high based on their intracellular expression of IDO, we detected higher levels of immune-regulatory factors (IL-10, PD-L1, and CTLA-4) in IDOhigh samples compared to IDOlow samples." (PMID 32782249, 2020). "Here, we showcase the ability of this novel model to recapitulate early invasive features and a previously recognized role for IL-10 in myeloid suppression and immune escape of metastatic melanoma, that is not adequately represented by classical 2D melanoma monolayer cultures." (PMID 32507967, 2020). "Moreover, eTregs produce inhibitory cytokines (TGF-b, IL-10, IL-35) to promote B lymphocyte-induced maturation protein (BLIMP1)-dependent exhaustion of CD8+ TILs in the tumor microenvironments of B16 melanoma and the BrafPten melanoma model." (PMID 32707850, 2020). "For B16-F10 melanoma cells, although not identified, likely the reduced tumor control in vivo was related to increased inhibition of T cell responses from either elevated cytokine production (IL-10, TGF-β) or ligation of PD-1." (PMID 31602007, 2019).
melanoma (continued). "The data presented here are consistent with our previous results showing an absence of IL-10 release after incubation of human PBMCs with human melanoma cells expressing the TM protein of HERV-K, with human cells producing PERV and with human cells expressing the TM protein gp41 of HIV-1." (PMID 30001404, 2018). "Since IL-10 is known to play an important role in B-1 biology, we hypothesized that the cytokine could be involved in the behavior alteration that is observed in the case of the B16F10 melanoma cells." (PMID 29145406, 2017). "Furthermore, inflammatory TH2-biased conditions such as IL-10, IL-4, VEGF and FoxP3+ Tregs that support class switching to IgG4 rather than IgE, and elevated IgG4 levels have been reported in different tumors including melanoma." (PMID 27471625, 2016). "Indeed, whereas the blood vessels were all but absent in the surrounding tissue of IL-10 secreting melanoma tumors, the tissue surrounding non-IL-10 producing tumors was highly vascularized." (PMID 26217588, 2015). "Importantly, the same anti-IL-10 mAb added in vitro (20 μg/ml) to B16/F10 melanoma cell culture did not change either cell proliferation rate or cell viability, ruling out the possibility of any direct toxic effect (not shown)." (PMID 23663506, 2013). "Furthermore, IL-10 DC have been shown to induce anergic regulatory CD4+ and CD8+ T cells (iTregs), which inhibit activated cytotoxic and helper T cells, resulting in a failure to kill melanoma cells." (PMID 21818385, 2011). "Because IL-10 plays an important role in the immune escape of tumors and neutralizing IL-10 has been proposed as a novel anti-tumor therapy, downregulation of HLA-DR through LPA-induced IL-10 production might be an important pathway in the progression, metastasis, and immune escape of melanoma." (PMID 39187677, 2025). "However, IL-10 was not widely expressed in neither group of melanoma cell lines." (PMID 39736644, 2024). "Here, we found M-CSF and TGFβ secreted from SK-MEL-28-RhS to also play a role in the SK-MEL-28-RhS-mediated immune modulation, which might explain why IL-10 blockade alone was not sufficient to reverse the melanoma-induced conversion of monocyte into M2-like cells." (PMID 37345186, 2023). "However, melanoma cell lines did not produce IL-10 cytokine in our experiments." (PMID 36194602, 2022). "In this context, our findings give emphasis to whether or not melanoma cells express IL-10Rα, as the expressing cells proliferated in the presence of IL-10 – which may be produced by melanoma environment – while the non-expressing melanoma cells were unresponsive to the cytokine." (PMID 26631117, 2015). "On the systemic level, we detected tapeworm-specific production of IL-4, IL-10, and IFN-γ by splenocytes isolated from infected mice, but no melanoma-specific cytokine response was observed." (PMID 38571957, 2024). "Occasional CD163+ TAMs that strongly express IL-10 transcripts were observed in the melanoma TME, although the vast majority of CD163+ TAMs were negative for IL-10 mRNA." (PMID 38903497, 2024). "In melanoma cells (A375 and H1205-lu), the expression of MMP9 and AMPK decreased in A375 cells after stimulation with IL-10 (20 ng/mL), while BCL-2 did not change significantly." (PMID 35893303, 2022). "Compared with metastatic primary tumors, B cell infiltrates in melanoma metastases were enriched in both LTA+ memory-like and LTA+ activated B cells, but not in any of the IL-10+ B cell subpopulations." (PMID 34359321, 2021). "Rb9 did not modify the melanoma lysate response in relation to IL-12, TNF, and IL-10 secretion but significantly reduced IL-6." (PMID 32010152, 2019). "Although a previous study demonstrated that IL-10, itself, was unable to modulate the B16F10 behavior, its influence on the cross-talk between the B-1 lymphocytes and the melanoma cells was not clear." (PMID 29145406, 2017).
melanoma (continued). "Reported tumor-permissive properties of B cells include B cell-dependent inhibition of antitumor immunity in lymphoma and melanoma (but not in sarcoma), through a CD40L-dependent mechanism that affects IL-10 secretion in vitro." (PMID 28507802, 2017). "Accordingly, the combinatorial administration of the anti-IL10 mAb, but not its related isotypic control (not shown), to gp10025-33 peptide-pulsed DC vaccinated mice led to a complete protection from B16F10 melanoma growth." (PMID 23663506, 2013). "Another study also found greater levels of expression of IL-10, IFN-γ, and IDO in SLN with metastasis than non-SLN in patients with melanoma." (PMID 19604349, 2009). "CXCL9, CXCL10, PD-L1, CD86, IL-10, TREM2, GPNMB, IL-4l1 and FOLR2 markers showed widespread expression by most melanoma TAMs, with no definition of a particular macrophage subset, and regardless of whether the tumor was metastasizing or not." (PMID 40406129, 2025). "Furthermore, more broad investigations into the phenotype and function of TGF-β or IL-10-producing regulatory and IFN-γ- or TNF-α-expressing inflammatory B cells in human melanoma are still lacking." (PMID 35909944, 2022). "In Braf/Pten melanoma-draining LNs, TSLP promoted not only GATA3+ Th2 cells, but also GATA3+ Tregs expressing a specific signature including ST2, CCR8, ICOS, PD-1, CTLA-4, OX40, and IL-10 — but not Th2 cytokines IL-4 and IL-13." (PMID 36107619, 2022). "We also evaluated the protein amount of a set of 12 cytokines and chemokines, including IL-2, IL-4, IL-5, IL-6, IL-10, IL-12, IL-17A, TNF-α, IFN-γ, MCP-1, MIP-1α, and eotaxin in TIF and plasma samples of C57BL6 mice, engrafted or not engrafted with B16 melanoma cells." (PMID 34604232, 2021). "In a first analysis including the entire cohort of recruited patients (in situ and stage I–IV melanoma patients), the amount of GM‐CSF, IL4, IL‐6, IL‐10, IL‐17A, and TGF‐β detected in serum was independent of the age of the melanoma patients and it did not vary between the sexes." (PMID 32485045, 2020). "We also found that inhibition of MAPK signaling pathway in human melanoma cells by genetic depletion of mutant BRAF or specific inhibitors reduced production of multiple immunosuppressive cytokines such as IL-6, IL-10, and VEGF, in most cases without affecting cell viability." (PMID 23755373, 2013). "On the other hand, our studies indicate that therapeutic treatment of mice with the TLR4/9 agonist complex after inoculation of B16F10 melanoma cells can not reverses tumor cell-induced STAT3 activation, IL-10 expression, and autophagy suppression in the lung tissues." (PMID 21931823, 2011).
Allergy (351 papers, 2002 to 2026). An allergy is an immune response or reaction to substances that are usually not harmful. "Other genes, including CD14, FOXP3, STAT6, SPINK5, IL-10 and IL-13, have demonstrated polymorphisms that affect allergy prevalence as well." (PMID 40004029, 2025). "A novel subset of interleukin (IL)-10 producing ILC2s are associated with tolerance following immunotherapy to grass pollen, house dust mite allergy and lipid transfer protein allergy." (PMID 39132724, 2024). "IL-6 rs1800795G allele (in particular GG genotype) was increased in the allergy patient group as well as IL-10 rs1800896AA genotype and IL-10RB rs2834167G/* positive genotypes." (PMID 39202464, 2024). "Complications during pregnancy were linked to different pattern of the IFNG, IL5, IL4 and IL10 methylation depending on allergy status." (PMID 37520545, 2023). "The deficiency of IL-10 induces Th17 cell differentiation and reduces Treg formation, thus causing allergies, autoimmunity and infection." (PMID 37275919, 2023). "In contrast, Gammaproteobacteria have been linked to protection from allergy through IL-10 induction." (PMID 35265075, 2022). "All of these signals are instrumental to Breg expansion and function; thus dysfunction leads to impaired IL-10 production and susceptibility to inflammation and allergy." (PMID 34867940, 2021). "Still, it is unclear how allergy factors work in the pathway underlying the PD-L1-mediated increases in IL-10." (PMID 34769327, 2021). "Breg cells have a negative regulatory capacity by secreting IL-10 in allergic diseases while acting as a tolerance hallmark following AIT." (PMID 34804031, 2021). "The function of IL‐10 is immunosuppressive and it is particularly associated with allergic diseases." (PMID 34435757, 2021). "In a murine model for hen's egg allergy, 2'FL or 6'SL were found to reduce allergy symptoms in association with the induction of IL-10+ Treg cells." (PMID 32457747, 2020). "Induction of Tregs and IL-10 production is also implicated in allergy-suppressive actions of the gastrointestinal mouse parasite H. polygyrus." (PMID 33013887, 2020). "Severe allergy is known to induce IL-10-producing ILC2s, which are associated with decreased eosinophil recruitment in the lung." (PMID 30893794, 2019). "In our experiments, there was a significant reduction in the level of IL-10 in the groups treated with 3 g/kg and 6 g/kg RE, which suggests that rhubarb caused a slight allergic reaction." (PMID 31852975, 2019). "It is well-established that IL-10 plays a crucial role in providing protection against infections, generating cancer immunity and inducing immune tolerance in Th-2 associated allergic diseases." (PMID 31134057, 2019). "Others have shown that IL-10 single nucleotide polymorphisms were associated with airway hyper-responsiveness, allergy, COPD, and high IL-10 levels." (PMID 30176916, 2018). "Variants of the Il10 gene locus that cause decreased IL-10 production are positively associated with allergy, but are also negatively associated with helminth infection." (PMID 29196657, 2017). "The prevention of allergy is known to be associated with the downregulations of IL‐4, IL‐5, IL‐13 and IL‐10." (PMID 28165193, 2017). "Regulatory B cells usually express high levels of IL-10 and have been linked to immune responses in different disease states, such as regulation of auto-immunity, allergic disease and helminth infections." (PMID 28871201, 2017). "IL-10 is a pleiotropic, immune regulatory cytokine that is important in protecting the host from infection-associated diseases, autoimmunity and allergy." (PMID 26875192, 2016). "It has also been reported that children at high risk of developing allergies have lower IL-10 production by mononuclear cells stimulated with allergens." (PMID 26907333, 2016).